MRPL35 (mitochondrial ribosomal protein L35)
Synonyms: L35mt; MRP-L35; bL35m
Tractability: Small molecule: a structure with a bound ligand is known. PROTAC: its protein half-life has been measured.
Gene: Protein-coding gene on chromosome 2 (86,199,355 to 86,213,790, forward strand). Ensembl gene ENSG00000132313.
Subcellular location: Mitochondrion
Pathways (Reactome):
Metabolism of proteins: Mitochondrial ribosome-associated quality control; Mitochondrial translation elongation; Mitochondrial translation initiation; Mitochondrial translation termination
Gene Ontology:
Molecular function: structural constituent of ribosome
Biological process: mitochondrial translation; translation
Cellular component: mitochondrial large ribosomal subunit; mitochondrion; mitochondrial inner membrane; mitochondrial ribosome; ribosome
Genetic constraint (gnomAD): Loss-of-function variants: 18 observed, 21.18 expected, observed/expected ratio (o/e) 0.85, 90% interval 0.59 to 1.26. The upper end of that interval is the gene's LOEUF score, 1.26, which puts it in group 5 of 6, group 1 being the genes least tolerant of losing a copy. Missense variants: 218 observed, 228.14 expected, observed/expected ratio (o/e) 0.96, 90% interval 0.86 to 1.07. Synonymous variants: 85 observed, 88.32 expected, observed/expected ratio (o/e) 0.96, 90% interval 0.81 to 1.15.
Homologues: Orthologues: chimpanzee MRPL35 (99% identical), macaque MRPL35 (95% identical), rabbit MRPL35 (81% identical), dog MRPL35 (78% identical), mouse Mrpl35 (77% identical), pig MRPL35 (76% identical), rat Mrpl35 (71% identical), guinea pig MRPL35 (69% identical), tropical clawed frog mrpl35 (60% identical), zebrafish mrpl35 (52% identical), Drosophila melanogaster mRpL35 (38% identical), Caenorhabditis elegans mrpl-35 (23% identical).
Diseases named in the same sentence as MRPL35 in open-access papers:
MRPL35 is named in the same sentence as 8 diseases in open-access papers, as found by Europe PMC text mining. Sharing a sentence is not in itself a finding about the gene and the disease. The quoted sentences say what the papers report.
gastric cancer (4 papers, 2024 to 2025). A primary or metastatic malignant neoplasm involving the stomach. "For example, high MRPL35 expression was found in gastric cancer (GC), and the deficiency of MRPL35 suppressed GC growth." (PMID 38987867, 2024). "In gastric cancer, increased expression of MRPL35 is associated with metastasis and advanced stage, with in vivo knockdown inhibiting tumour formation and promoting apoptosis." (PMID 39354291, 2024). "18-GRA inhibits cell proliferation and tumor growth and promotes apoptosis by downregulating MRPL35 in gastric cancer patients." (PMID 39859078, 2025). "MRPL35 is upregulated in several types of cancer, including lung cancer, CRC, gastric cancer, and HCC, and its overexpression is associated with a worse prognosis in these cancer types." (PMID 39859078, 2025). "MRPL35 knockdown induces apoptosis in gastric cancer cells, inhibits their proliferation and colony formation, and suppresses tumor growth by regulating BCL-XL, PICK1, and AGR2." (PMID 39859078, 2025). "Increased MRPL35 expression is associated with poor survival outcomes across NSCLC, colorectal, and gastric cancers." (PMID 39354291, 2024). "MRPL35 may play important roles in cancer progression and confer multidrug resistance, particularly in relation to gastric cancer and lung cancer." (PMID 39859078, 2025). "High MRPL35 expression is correlated with an advanced stage of gastric cancer." (PMID 39859078, 2025). "Together, these findings suggest MRPL35 may have an application as a therapeutic target across a range of cancers, however further investigations beyond gastric cancer are required." (PMID 39354291, 2024). "This indicates that MRPL35 may play a significant role in the development and progression of gastric cancer, with its high expression potentially enhancing the proliferation and anti-apoptotic capabilities of gastric cancer cells, thereby affecting disease progression and prognosis." (PMID 40371222, 2025). "Later investigation by the same authors found that treatment of gastric cancer cell lines (BGC-823, MGC80-3) with 18β-glycyrrhetinic acid, a promising anti-inflammatory and antioxidant agent, inhibited MRPL35 expression and induced cancer cell apoptosis and cell cycle arrest." (PMID 39354291, 2024).
colorectal cancer (3 papers, 2023 to 2025). A primary or metastatic malignant neoplasm that affects the colon or rectum. "MRPL35 is highly expressed in colorectal cancer tissues, and its high expression is significantly associated with shortened OS in patients." (PMID 40371222, 2025). "In a colorectal cancer xenograft model in nude mice, knockdown of MRPL35 effectively inhibits tumor proliferation." (PMID 40371222, 2025). "Likewise, MRPL35 is abundantly expressed in colorectal cancer, and its suppression leads to hindered cell proliferation and ultimately cell death." (PMID 40918472, 2025). "Additionally, MRPL35 was remarkably overexpressed in colorectal cancer, while higher MRPL35 expression was correlated with a shorter OS in these patients." (PMID 36769082, 2023).
lung carcinoma (2 papers, 2024 to 2025). "According to the TCGA, CPTAC, and ENCORI databases, we found that MRPL35 levels were higher in lung cancer tissues than in normal tissues." (PMID 38987867, 2024). "Mitochondrial ribosomal protein L35 (MRPL35) has been reported to contribute to the growth of non–small cell lung cancer (NSCLC) cells." (PMID 38987867, 2024).
non-small cell lung carcinoma (2 papers, 2023 to 2025). A group of at least three distinct histological types of lung cancer, including non-small cell squamous cell carcinoma, adenocarcinoma, and large cell carcinoma. "Mitochondrial ribosomal protein L35 (MRPL35) is found to be highly expressed in non-small cell lung cancer (NSCLC) cells, and the anticancer effect of MRPL35 silencing can be rescued by promoting SLC7A5 expression." (PMID 40598593, 2025).
lymph node metastasis (1 paper, 2024). "Additionally, higher MRPL35 expression was correlated with advanced TNM stages, lymph node metastasis, and big tumor size." (PMID 38987867, 2024).
cancer (6 papers, 2017 to 2025). A tumor composed of atypical neoplastic, often pleomorphic cells that invade other tissues. "MRPL35 encoded Mammalian mitochondrial ribosomal protein, whose impact on cancers has rarely been reported." (PMID 28796930, 2017). "Herein, we observed decreased glutamine consumption, α‐KG production, and glutamate generation after MRPL35 silencing in NSCLC cells, implying that MRPL35 silencing induced glutamine metabolism inhibition to prevent cancer cells from gaining energy." (PMID 38987867, 2024). "The results of statistical analysis further confirmed that MRPL35 was over-expressed in cancer tissues." (PMID 38093266, 2023). "The genetic inhibition of MRPs, such as MRPL35, may prevent NSCLC growth by blocking the dependence of cancer cells on glutamine metabolism, which may provide a novel insight into the development of molecular targeted therapy for NSCLC patients." (PMID 38987867, 2024).
tumor (5 papers, 2023 to 2025). "MRPL35 knockdown inhibits cell proliferation and tumor growth in CRC by triggering the accumulation of ROS, which subsequently leads to DNA damage, thereby suppressing the disease progression in CRC." (PMID 39859078, 2025). "Subsequently, the volume and weight of tumor were measured, which were significantly reduced in MRPL35-knockdown group." (PMID 38093266, 2023). "In the tumor microenvironment, glutamine metabolism is an important regulatory mechanism to provide energy for tumors, and SLC7A5 and MRPL35 are important regulators of this mechanism." (PMID 40672756, 2025). "MRPL35 expression was stabilized by USP39‐induced deubiquitination in NSCLC cells, and knockdown of MRPL35 suppressed NSCLC cell proliferation, invasion, and glutamine metabolism in vitro and impeded tumor growth in vivo by upregulating SLC7A5, providing a promising therapeutic target for NSCLC." (PMID 38987867, 2024).
MRPL35 also shares sentences with these, for which no sentence is quoted: Obesity (1 paper).